ACR (acrosin)
Description:
Acrosin is the major protease of mammalian spermatozoa. It is a serine protease of trypsin-like cleavage specificity, it is synthesized in a zymogen form, proacrosin and stored in the acrosome.
Synonyms: SPGF87
Tractability: Small molecule: a high-quality ligand is known; it belongs to a druggable protein family. Antibody: its Gene Ontology location is reachable by antibodies, with high confidence; UniProt predicts a signal peptide or a membrane-spanning region. PROTAC: a small molecule that binds it is known.
Target class: Serine protease; Enzyme; Serine protease PA clan; Serine protease S1A subfamily; Protease
Gene: Protein-coding gene on chromosome 22 (50,738,196 to 50,745,339, forward strand). Ensembl gene ENSG00000100312.
Pathways (Reactome):
Reproduction: Acrosome Reaction and Sperm:Oocyte Membrane Binding
Gene Ontology:
Molecular function: D-mannose binding; protein binding; serine-type endopeptidase activity; amidase activity; copper ion binding; DNA binding; fucose binding; protease binding; serine-type peptidase activity; zinc ion binding; peptidase activity
Biological process: acrosome reaction; activation of adenylate cyclase activity; acrosome matrix dispersal; single fertilization; penetration of zona pellucida; protein catabolic process; proteolysis; response to steroid hormone
Cellular component: nucleus; protein-containing complex; acrosomal matrix; extracellular region; acrosomal vesicle; Golgi-associated vesicle
Genetic constraint (gnomAD): Loss-of-function variants: 17 observed, 27.05 expected, observed/expected ratio (o/e) 0.63, 90% interval 0.43 to 0.94. The upper end of that interval is the gene's LOEUF score, 0.94, which puts it in group 4 of 6, group 1 being the genes least tolerant of losing a copy. Missense variants: 371 observed, 445.63 expected, observed/expected ratio (o/e) 0.83, 90% interval 0.76 to 0.91. Synonymous variants: 167 observed, 174.43 expected, observed/expected ratio (o/e) 0.96, 90% interval 0.84 to 1.09.
Homologues: Orthologues: chimpanzee ACR (97% identical), macaque ACR (93% identical), dog ACR (71% identical), guinea pig ACR (71% identical), mouse Acr (67% identical), pig ACR (67% identical), rat Acr (67% identical).
Diseases named in the same sentence as ACR in open-access papers:
ACR is named in the same sentence as 22 diseases in open-access papers, as found by Europe PMC text mining. Sharing a sentence is not in itself a finding about the gene and the disease. The quoted sentences say what the papers report.
infertile (9 papers, 2013 to 2025). "Although research has suggested that abnormal sperm acrosin activity is a potential cause of infertility, this test can only be applicable to fresh semen, and the procedure is cumbersome and time-consuming." (PMID 38212716, 2024). "Therefore, the total acrosin activity could be used as an indicator for the clinical evaluation of unexplained causes of infertility." (PMID 40599651, 2025). "VASA and acrosin basal levels were found to be lower in infertile patients compared to the OA group (8.2% vs. 30.6% and 12.8% vs. 30.5%, respectively; p < 0.05)." (PMID 36769720, 2023). "Most importantly, contrary to rat and mouse ACR-KO ablation models, ACR gene ablation rendered male hamsters completely infertile due to a failure of sperm-zona penetration." (PMID 33445482, 2021). "In this regard, the observation that recombinant human proacrosin/acrosin binds to rhZP2 and the presence of acrosin antibodies in sera from infertile women supports the participation of acrosin in the process of fertilization." (PMID 26329136, 2015). "Nevertheless, the loss of acrosin protease activity does not lead to infertility in mice and spermatozoa from knock-out mice can penetrate zona pellucida of the oocyte." (PMID 23675907, 2013). "Also, Acrosin, a trypsin-like serine protease in the sperm acrosome, mediates sperm passage through the zona, and gene deletion in consanguineous men and hamsters leads to infertility." (PMID 38764035, 2024). "For example, the genetic ablation of Acrosin results in no fertility phenotype in mice, subfertility in rats, or complete infertility in hamsters and humans." (PMID 38764035, 2024).
varicocele (3 papers, 2015 to 2020). A condition characterized by the dilated tortuous veins of the spermatic cord with a marked left-sided predominance. "The reduced expression of acrosin precursor suggests the impairment of the spermatogenesis process in varicocele patients." (PMID 25890347, 2015). "We found acrosin precursor to be underexpressed in the unilateral varicocele patients and present in very low abundance." (PMID 25890347, 2015). "Other proteins associated with normal sperm functions, such as SEMG1 and SEMG2, acrosin (ACR), elongation factor 1-gamma (EEF1G) and PGK2 were downregulated in SP from varicocele, probably explaining the poor sperm motility and concentration usually found in these patients." (PMID 32987677, 2020).
diabetes (2 papers, 2022 to 2023). "The percentage of people being tested varied from 13% of the hypertension cohort for ACR or microalbumin testing, to 96% of the diabetes cohort having renal function or HbA1c tests." (PMID 36693759, 2023).
male infertility (2 papers, 2022 to 2025). The inability of the male to effect fertilization of an ovum after a specified period of unprotected intercourse. "Although acrosin-deficient male mice are fertile, disruption of hamster acrosin resulted in complete male infertility." (PMID 35600599, 2022).
autism (1 paper, 2011). Persistent deficits in social interaction and communication and interaction as well as a markedly restricted repertoire of activity and interest as well as repetitive patterns of behavior. "Two of our patients with interstitial microdeletions disrupting SHANK3 and ACR only (P38, P43) fulfill the clinical criteria for a diagnosis of autism, while the others (P37, P42, P44), do not." (PMID 21779178, 2011).
diarrhoea (1 paper, 2012). "The same differences in TFRC expression were not only found between the F4ab/acR- and F4ab/acR+ piglets without diarrhoea, but also between the F4ab/acR+ piglets with and without diarrhoea." (PMID 23061722, 2012).
enteritis (1 paper, 2016). Inflammation of the small intestine. "Efficient strategies for treating enteritis caused by F4+ enterotoxigenic Escherichia coli (ETEC)/verocytotoxigenic Escherichia coli (VTEC)/enteropathogenic E. coli (EPEC) in mucin 4 resistant (MUC4 RR; supposed to be F4ab/ac receptor–negative [F4ab/acR−]) pigs remain elusive." (PMID 27424033, 2016).
kidney damage (1 paper, 2023). "Positive relationships also occurred between the markers of kidney damage determined in the urine (KIM-1, β2-MG, NAG, ALP, ACR, and PCR) and the serum concentrations of uric acid and urea, except for a lack of relationship between the serum concentration of uric acid and ALP activity and PCR." (PMID 37511414, 2023).
tuberculosis (1 paper, 2017). A chronic, recurrent infection caused by the bacterium Mycobacterium tuberculosis. "Of note, anti-ACR IgG showed higher titer in Beijing MTB infected tuberculosis (TB) patients than in HC (Kruskal–Wallis test, p < 0.05), while the levels of anti-Ag85B, anti-TBGL, anti-TDM-K, and anti-TDM-M IgG were higher in non-Beijing TB patients than in HC." (PMID 28182078, 2017).
ACR also shares sentences with these, for which no sentence is quoted: acute lymphoblastic leukemia (1 paper); Azoospermia (1); cancer (1); dengue (1); diabetic nephropathy (1); Hypertension (1); inflammatory skin disease (1); lung disease (1); lymphoma (1); ptosis (1); schizophrenia (1); thymic tumors (1); tumor (1).